BRCA1 (BRCA1 DNA repair associated)
Diseases named in the same sentence as BRCA1 in open-access papers (continued):
Sharing a sentence is not in itself a finding about the gene and the disease.
cancer (continued). "HBOC is a condition that increases the probability of developing breast, ovarian and other types of cancer, such as pancreatic and prostate cancer, due to the presence of germline mutations in genes of greater susceptibility, such as BRCA1 or BRCA2." (PMID 40259910, 2025). "International studies have shown that the uptake of risk-reducing surgeries among BRCA1/2 carriers varies widely, influenced by factors such as age, country of residence, perceived cancer risk, cultural norms, and access to genetic counseling." (PMID 40390061, 2025). "The first approved synthetic lethal drug, a PARP inhibitor targeting poly ADP‐ribose polymerase (PARP), has demonstrated efficacy against cancer cells with specific genetic mutations, such as BRCA1 or BRCA2 mutations." (PMID 40859871, 2025). "Homologous recombination fails in BRCA1-deficient cancers, so their genomes have random mutations that can turn on oncogenes or turn off tumor suppressors, making them more aggressive." (PMID 40584290, 2025). "These drugs are particularly effective in cancers that already have deficiencies in DNA repair mechanisms, such as those with mutations in the BRCA1 and BRCA2 genes." (PMID 40127955, 2025). "PARP inhibitors (PARPis) are drugs that exploit synthetic lethality to target cancer cells that have defects in DNA repair pathways, such as those caused by mutations in BRCA1 or BRCA2 genes." (PMID 39996890, 2025). "This is related to the growing importance of PARP inhibitors in cancer therapy, and the presence of BRCA1 or BRCA2 mutations is a good predictive marker that indicates the probable high effectiveness of PARP inhibitors in therapy." (PMID 40429755, 2025). "This innovative therapeutic paradigm transcends traditional DNA repair-centric approaches, offering novel combinatorial strategies for BRCA1-deficient cancers." (PMID 40342999, 2025). "Pathogenic/likely pathogenic (P/LP) germline variants (PGVs) in cancer-predisposing genes, mostly in BRCA1 and BRCA2 have been linked to the etiology of breast and many other cancers." (PMID 41568010, 2025). "This is evidenced by the cancer predisposition associated with germline mutations in BRCA1, BRCA2, and other HR genes, as well as by the frequent somatic suppression of HR observed in sporadic cancers, where it acts as a driver of tumorigenesis." (PMID 41463247, 2025). "For example, alternative splicing can allow cancer cells to bypass germline BRCA1 mutations, contributing to therapeutic resistance." (PMID 40781225, 2025). "Interest in PARP inhibitors has increased since blocking PARP1 results in notable cell death in cancer cells with gene mutations, including BRCA1 and BRCA2." (PMID 40141415, 2025). "This is because BRCA1/2 mutations impair DNA repair mechanisms, making cancer cells more susceptible to DNA-damaging agents such as platinum." (PMID 40141188, 2025). "Studies have shown that loss of BRCA2 leads to cells being 100 to 1000 times more sensitive to PARPi, this led to their exploitation in the clinic in the context of BRCA1/2-mutated cancer." (PMID 41347092, 2025). "Breast Cancer Genes 1 and 2 (BRCA1/2) are involved in DNA homologous recombination repair and are typically included in germline gene panels for testing genetic predisposition to cancer." (PMID 39838196, 2025). "These agents exploit the defective DNA repair machinery in BRCA1/2-mutated cancers—a phenomenon often described as “BRCAness”—and have been linked to improved therapeutic responses." (PMID 40870889, 2025). "The frequencies of BRCA1/2 variants in regional areas were compared with those of healthy individuals or nationwide cancer cohorts to investigate regional distribution." (PMID 40249378, 2025). "The most concordant cancer susceptibility genes represented in the combined data were BRCA1, BRCA2 and ATM, with 13, 11, and 6 pathogenic/likely pathogenic germline variants, respectively." (PMID 41465149, 2025).
cancer (continued). "BRCA1-associated cancers often have MRI findings consistent with the BI-RADS characteristics of TNBC51, present as masses with oval shape, well-defined circumscribed margin, and rim-enhancement." (PMID 41083355, 2025). "Over the last decade, PARPi have been used as monotherapy and in combination with other therapeutics for the treatment of other HDR-deficient cancers, most notably BRCA1/2-mutated cancers." (PMID 41357766, 2025). "Nevertheless, studies find that people with BRCA1/2 and BO often wrongly estimate their cancer risk." (PMID 39812114, 2025). "Dominant cancer‐associated pathogenic and likely pathogenic variants were identified in BRCA1 and MET, and two patients were carriers of recessive pathogenic BLM variants." (PMID 39344744, 2025). "Considering the wide use of PARP inhibitors in BRCA1/2-mutated cancers, we suggest that our resistant model should be very valuable in developing drugs to overcome resistance." (PMID 40274769, 2025). "The majority of BRCA/Lynch MINAS developed with both Lynch- and BRCA1/2-associated cancers and presented with multiple malignancies over their lifetime." (PMID 39843919, 2025). "As the first drug developed based on the principle of synthetic lethality, PARPi has provided clinical benefits to cancer patients with BRCA1/2 mutations." (PMID 40764600, 2025). "Pol β as a synthetically lethal target within BRCA1-deficient cells and a potentially useful one for treating cancer." (PMID 41568291, 2025). "Collectively, these observations provide important evidence that PARP1 trapping is a key mechanism in driving the effectiveness of PARPi in BRCA1-mutated cancer cells." (PMID 41459749, 2025). "Receiving a positive BRCA1/2 test result can significantly impact psychological well-being, as individuals face complex decisions regarding cancer risk management." (PMID 40390061, 2025). "When near-complete and complete responses were combined, the difference between BRCA2- and BRCA1-associated cancers remained significant [9/15 (60%) vs. 12/48 (25%), Fisher’s exact test, two-tailed, P = 0.02]." (PMID 40547808, 2025). "PARP inhibitors are effective in cancers with homologous recombination (HR) defects, particularly BRCA1/2-mutated tumors." (PMID 41243111, 2025). "This dual application of our data enhances the clinical interpretation of BRCA1 variants, contributing to more accurate genetic counselling and improved cancer risk assessment." (PMID 40966517, 2025). "This is a well-described Olaparib resistance development strategy for cancer patients with similar BRCA1 mutations." (PMID 40669753, 2025). "BRCA2-associated HGSOCs had a significantly higher rate of pCRs as compared to BRCA1-mutated cancers [8/15 (53%) vs. 7/48 (15%), Fisher’s exact test, two-tailed, P = 0.004]." (PMID 40547808, 2025). "Among all cancers, both the germline and somatic mutation frequencies of BRCA1 or BRCA2 in HGSOC are the highest." (PMID 40830526, 2025). "PDS causes DNA damage and apoptosis in BRCA1/2-deficient cancer cells, including cells resistant to PARP inhibition." (PMID 40833407, 2025). "We next wanted to extend our findings from HeLa cells into cancer cell lines bearing pathogenic BRCA1 or ATM mutations." (PMID 39994444, 2025). "Loss of PTEN activity enhances PI3K/AKT signaling, interferes with DSB repair, and promotes the growth of BRCA1-deficient cancer cells by upregulating BRCA1 expression." (PMID 41155174, 2025). "Human TATDN2 has recently been found to function as a structure-specific RNase to resolve R-loops in vitro and be required for the response to replication stress in BRCA1-deficient cancer cells." (PMID 41404808, 2025). "The study presented here employed a multi-pronged proteomics approach to explore the consequential cellular response to MX treatment and the expansive binding profile of mitoxantrone to gain insight into MX sensitivity in BRCA1-deficient cancer." (PMID 41283651, 2025).
cancer (continued). "Yet, the precise connection between their DNA repair functions and their capabilities in processing R-loops, particularly in the context of cancer-associated mutations in BRCA1/BRCA2, remains elusive." (PMID 40271193, 2025). "In cancer cells, mutations that disrupt these heterodimers can lead to the detrimental degradation of both BRCA1 and BARD1 proteins." (PMID 40805222, 2025). "Olaparib (OL), a PARP inhibitor with a molecular weight of 435.08 g/mol and a formula structure of C24H23FN4O3, has revolutionized cancer therapy, particularly for BRCA1/2-mutated cancers." (PMID 39996825, 2025). "Clinical and pathogenic characteristics of cancers with GDH for BRCA1 and BRCA2 depend on the genes somatically mutated in wild alleles." (PMID 40601170, 2025). "Over time, the CWS has been adapted, validated and extensively used in various context among cancer survivors and in populations with hereditary cancer risk, such as BRCA1/2 carriers." (PMID 40390061, 2025). "RTx-284 also demonstrated strongsynergy with multiple PARPi in MDA-MB-436 and PE01 cancer cell linesharboring BRCA1 and BRCA2 pathogenic mutations, respectively." (PMID 41124685, 2025). "The therapeutic landscape of cancer treatment has been profoundly influenced by targeting BRCA1 and BRCA2 mutations, leading to innovative approaches and advancements in cancer therapy." (PMID 40004231, 2025). "A retrospective case–control study used data on 150,962 women tested with a multigene hereditary cancer panel to evaluate an 86-SNV PRS in BRCA1, BRCA2, CHEK2, ATM, and PALB2 P/LP variant carriers." (PMID 39858629, 2025). "We used four PARP inhibitors to validate the ability to detect synthetic lethality in BRCA1-deficient cancer cells." (PMID 40982437, 2025). "Consistently, an established cancer derived BARD1-binding-deficient-BRCA1 C61G mutant still interacts with Cdh1." (PMID 41359628, 2025). "ML is used to predict BC risk based on family history of cancer, BRCA1 or BRCA2 mutation status, hormonal makeup, and lifestyle to produce individualized risk scores." (PMID 40940896, 2025). "The existing literature clearly supports the protective role of MD and IF in limiting inflammation and possibly lowering the risk of cancer in patients with HCSs such as BRCA1/2 mutations." (PMID 41335382, 2025). "Reported cancer penetrance for these germline mutations is highly variable, and even individuals within the same family carrying an identical BRCA1/2 alteration can exhibit markedly different risk profiles." (PMID 40904409, 2025). "As reported in the Introduction section, different PARPi were developed to induce synthetic lethality in cancer patients harbouring BRCA1/2 mutations and HR deficiencies, leading to selective cancer cell death." (PMID 40091075, 2025). "The clinical success of PARPi in BRCA1/2-deficient cancers underscores the potential of synthetic lethal strategies to address previously hard-to-treat malignancies." (PMID 40982437, 2025). "Positive lymphovascular invasion, a high Ki-67 index, multifocality, prior cancer history, and inheritance of germline gene variants such as BRCA1 and BRCA2 also contribute to a poorer prognosis." (PMID 40831739, 2025). "pCRs were observed in 38/69 (55%) BRCA1 mutation carriers vs. 13/36 (36%) BRCA2-associated cancers (Fisher’s exact test, two-tailed, P = 0.1) or 43/150 (29%) BRCA-WT tumors (Fisher’s exact test, two-tailed, P = 0.0003)." (PMID 40547808, 2025).
cancer (continued). "Unlike well described hereditary cancer risk syndromes such as BRCA1/2, this is the first study to evaluate the prognosis of cancer in patients with germline pathogenic variants in PTEN (i.e. in individuals with PHTS)." (PMID 40468016, 2025). "PARP inhibitors are standard for BRCA1/2-mutant or homologous-recombination–deficient (HRD) cancers." (PMID 41583426, 2025). "The PGV rate was largely contributed to by BRCA2 (1.7%), ATM (1.3%), CHEK2 (1.1%) and BRCA1 (0.5%) and PGVs in these genes were found at significantly higher rates in the high risk localized and advanced PCa cohort compared to cancer-free males." (PMID 40832411, 2025). "Here, we present the prevalence and geographical distribution of BRCA1/2 variants in northeastern Japan, comparing it with that in the regional unaffected and nationwide cancer cohorts." (PMID 40249378, 2025). "People with a high-risk for developing cancers such as those who have inherited BRCA1/2 mutations or mutations in mismatch repair genes are natural choice for advancing the science of immunoprevention." (PMID 40437549, 2025). "The CS79-hiPSCs were harvested from a BRCA1 mutated invasive cancer patient and were then differentiated over the course of 13 days into BECs." (PMID 40371388, 2025). "Pathogenic germline variants in the BRCA1/2 genes lead to an increased lifetime risk of breast, ovarian and further less frequently present cancers in women and an increased lifetime risk of breast, prostate and other tumors in men." (PMID 40104509, 2025). "As a result, cancers with mutations in BRCA1/2 are highly susceptible to treatments that damage DNA, such as poly (ADP-ribose) polymerase (PARP) inhibitors." (PMID 39997609, 2025). "BRCA1 gene mutations vary based on genetic background, environmental factors, and family history of cancer." (PMID 40904409, 2025). "The risk of cancer with genetic alteration of BRCA1 is higher among females compared to males, and BRCA1-related cancers in females have an earlier average age of diagnosis compared to BRCA1-related cancers in males." (PMID 39724532, 2025). "Ivosidenib treatment confers an HR repair deficient phenotype and PARPi hypersensitivity to BRCA1/2-WT cancer cells." (PMID 40299557, 2025). "Cyclin D1 expression, which has an estrogen induction, was less frequent in BRCA1 than in BRCA2-mutated carcinomas, with gene amplification rates of 18% in BRCA1 and 60% in BRCA2." (PMID 40136510, 2025). "Other modifiers of cancer risk in BRCA1 carriers include microelements, of which, to date, only serum arsenic and blood lead levels have been proven to influence the risk." (PMID 38892720, 2024). "Sex differences in the epigenetic regulation of BRCA1 through DNAm have drawn significant interest due to their implications for cancer susceptibility." (PMID 39358554, 2024). "As we will discuss below, the loss of BRCA1/2 functions in cancer cells creates a dependency upon proper PARP functions and cycling for cell survival." (PMID 39007266, 2024). "This is particularly relevant for women who already face a higher cancer risk, especially BRCA1/2 pathogenic variant carriers." (PMID 38892081, 2024). "The dependence of cancers with BRCA1/BRCA2 mutations or other HRR defects on poly[adenosine diphosphate (ADP)-ribose] polymerase (PARP) enzymes to correct DSBs leads to apoptosis in the presence of PARPi." (PMID 38966174, 2024). "Here, we describe a 14-year-old patient with an isolated DOR, carrying compound heterozygous frameshift mutations in the breast cancer susceptibility gene type 1 (BRCA1)." (PMID 39596525, 2024).
cancer (continued). "Exploiting dependency on base excision repair for therapeutic purposes, PARP inhibition in BRCA1/2-mutated cancer cells induces unresolved DNA damage, leading to cell death." (PMID 38910707, 2024). "After 19 cycles of mFFX, comprehensive cancer genomic profiling (CGP) identified a BRCA1 pathogenic variant that was confirmed to be germline origin." (PMID 39188100, 2024). "Given the known high cancer risks associated with BRCA1 PVs (including under age 40), this would lead lower number of PV carriers in the sample." (PMID 39294438, 2024). "BRCA1-deficient cancer cells harbor a deficiency of DNA repair by HR, which makes these cells respond well to poly ADP ribose polymerase (PARP) inhibitors." (PMID 38627785, 2024). "This is expected given the central role of these proteins and pathways in cancer, the long IDRs of BRCA1 and BRCA2 and the large number of disease-associated mutations found in these regions." (PMID 39009827, 2024). "This leads to the death of cancer cells with BRCA1/BRCA2 mutations or homologous recombination deficiency." (PMID 39175508, 2024). "Cells deficient in breast cancer gene 1 or 2 (BRCA1 or BRCA2) function have a high level of chromosomal instability." (PMID 39085400, 2024). "Another mechanism by which BRCA1-mutated cancer cells regain HR function involves the loss of the protein 53BP1, which mediates the switch between repair of double-stranded DNA breaks from HR to nonhomologous end joining." (PMID 38165032, 2024). "In the overall MaBC and FBC cohorts, we compared mutational prevalence in cancer susceptibility genes (CSG) (ATM/BRCA1/BRCA2/CHEK2/PALB2)." (PMID 39049124, 2024). "The findings that GATA3 stimulates DSB repair through HR and reconstitution of Gata3 restores the HR efficiency of Brca1-deficient cancer cells prompting us to investigate the response of Gata3-deficient tumor cells to PARP inhibitor." (PMID 38627785, 2024). "Women with germline pathogenic mutations in BRCA1 or BRCA2 have a significantly higher lifetime risk of developing cancers in several organs, especially in the breast and ovaries." (PMID 38540206, 2024). "By binding to other proteins, BRCA1 plays a vital role in DNA repair, and BRCA1 mutations frequently occur during cancer development, causing cells to accumulate DNA damage." (PMID 39624096, 2024). "BRCA1/BRCA2-associated cancers are characterized by genomic instability, leading to large-scale copy number alterations." (PMID 39198848, 2024). "Understanding the cellular functions of BRCA1 helps identify new genes and proteins involved in cancer susceptibility and development." (PMID 38543119, 2024). "ATM missense variants have a similar effect as BRCA1 mutations on cancer cells, sensitizing the cancer cells to platinum-derived drugs." (PMID 38674216, 2024). "For example, we found a cancer-related D695Y mutation in the tumour suppressor Breast cancer type 1 susceptibility protein (BRCA1) that creates novel binding sites for the Yx[FILV]-binding FERM domains of Moesin (MSN) and Radixin (RDX)." (PMID 39009827, 2024). "To this purpose, we used Blg-Cre; Brca1F/F;Trp53F/F mice (hereafter referred to as Brca1p53-KO), an established mouse model of basal-like cancer closely resembling BRCA1-deficient human tumors." (PMID 38835038, 2024). "Apart from mesenchymal stromal cells, BRCA1 PVs also can influence cancer-associated fibroblasts (CAFs) to further promote metastasis of cancer cells." (PMID 39682099, 2024). "BRCA1 mutations increase the risk of various cancers, including breast, ovarian, male breast, prostate, colon, rectum, pancreatic, and stomach cancers." (PMID 38543119, 2024). "The concepts of synthetic lethality and BRCAness have established a framework for targeting BRCA1/2 mutant tumors and other HR-deficient tumors in cancer therapy." (PMID 39007266, 2024).